GLP1R (glucagon like peptide 1 receptor)
Diseases named in the same sentence as GLP1R in open-access papers (continued):
Sharing a sentence is not in itself a finding about the gene and the disease.
type 2 diabetes (continued). "Liraglutide is a glucagon-like-peptide-1 receptor agonist (GLP-1-RA) and is FDA-approved for type 2 diabetes as liraglutide 1.8mg and for obesity as liraglutide 3.0mg." (PMID 36699042, 2022). "The glucagon-like peptide-1 receptor (GLP-1R) is a class B G protein–coupled receptor and mainstay therapeutic target for the treatment of type 2 diabetes and obesity." (PMID 34315812, 2021). "The glucagon-like peptide-1 receptor (GLP-1R) is an important regulator of glucose homeostasis and has been successfully targeted for the treatment of type 2 diabetes." (PMID 34129856, 2021). "GLP-1R mediates a number of physiological effects, and due to its functions, the GLP-1R is a major therapeutic target for treatment of type 2 diabetes and obesity." (PMID 34497585, 2021). "Several GLP‐1 receptor (GLP‐1R) agonists are prescribed to patients with obesity and type 2 diabetes." (PMID 34319011, 2021). "The receptors for the glucagon-like peptide-1 (GLP-1R), glucose-dependent insulinotropic polypeptide (GIPR), and glucagon (GCGR) are major pharmacological targets in metabolic diseases such as type 2 diabetes (T2D) and obesity." (PMID 33268378, 2021). "The results of these studies demonstrated that GLP-1R agonists and DPP-4 inhibitors significantly upregulate the insulin response and can improve hyperglycemia in patients with type 2 diabetes." (PMID 34205264, 2021). "The glucagon-like peptide-1 receptor agonist (GLP-1RA) and dipeptidyl peptidase-IV (DPP-IV) inhibitor are very often used in subjects with type 2 diabetes mellitus (T2DM)." (PMID 34360682, 2021). "A significant reduction in the incidence of major cardiovascular events (MACE) has been observed in patients with type 2 diabetes mellitus (T2DM) treated with glucagon-like peptide-1 receptor agonists (GLP-1RA), suggesting the possibility of cardioprotective actions for some molecules of the class." (PMID 34526024, 2021). "Glucagon-like peptide-1 receptor (GLP-1R) agonists, including exenatide, are in common clinical use for reducing hyperglycemia in type 2 diabetes." (PMID 34673570, 2021). "Unimolecular dual agonists for the glucagon-like peptide 1 receptor (GLP1R) and glucagon receptor (GCGR) are emerging as a potential new class of important therapeutics in type 2 diabetes (T2D)." (PMID 33028880, 2020). "One such study, identified a glucagon-like peptide 1 receptor (GLP-1R) agonist, an FDA approved treatment for type II diabetes, as a potential therapy." (PMID 32397226, 2020). "GLP-1 analogues, activating the GLP-1 receptor (GLP1R), have been developed for the treatment of type 2 diabetes mellitus." (PMID 32635358, 2020). "Newer antidiabetic agents, such as sodium-glucose cotransporter-2 (SGLT-2) inhibitors and glucagon-like peptide-1 receptor agonists (GLP-1 RAs), decreased PWV in studies in patients with type-2 diabetes." (PMID 32718053, 2020). "Owing to their pleiotropic metabolic benefits, glucagon-like peptide-1 receptor (GLP-1R) agonists have been successfully utilized for treating metabolic diseases, such as type 2 diabetes and obesity." (PMID 32481528, 2020). "Recently, cardiovascular outcome study of GLP-1 receptor (GLP-1R) agonists showed reduction of cardiovascular events and prevention of chronic kidney disease progression in type-2 diabetic patients." (PMID 31537818, 2019). "The glucagon-like peptide-1 receptor (GLP-1R) agonist exendin-4 (Ex-4) is a long-acting analog of the endogenous insulinotropic peptide, which has been approved as a treatment for type 2 diabetes mellitus." (PMID 31779652, 2019). "One exception is the class of glucagon-like peptide-1 receptor (GLP-1R) agonists, which can be used to treat not only type 2 diabetes but obesity, hyperphagia, and hypertension." (PMID 29317623, 2018). "Glucagon receptor (GCGR) and glucagon-like peptide-1 receptor (GLP-1R), two clinically validated drug targets in patients with type 2 diabetes, were used as an example for functional divergence analysis." (PMID 28642113, 2017).
type 2 diabetes (continued). "Glucagon-like peptide-1 receptor agonists (GLP-1RAs) appear to have several beneficial effects on beta cell function, offering individuals with type 2 diabetes the potential for enduring glycaemic control." (PMID 28526920, 2017). "The Glucagon-like peptide-1 receptor (GLP-1R) is a member of the class B G protein-coupled receptor (GPCR) family and a well-established target for the treatment of type 2 diabetes." (PMID 27196125, 2016). "Recently, incretin-based therapies, dipeptidyl peptidase-4 inhibitors (DPP-4i) and glucagon-like peptide-1 receptor agonists (GLP-1RA), have become widely available for management of type 2 diabetes and are used especially in East Asia." (PMID 25944304, 2015). "Evidence suggests that the glucagon-like peptide-1 receptor (GLP-1R) agonist exendin-4 (EX-4), used in the treatment of type 2 diabetes mellitus, also displays neuroprotective properties in multiple cellular and in vivo models of neurodegenerative disorders." (PMID 26316987, 2013). "Novel incretin-based drugs, such as glucagon-like peptide-1 receptor agonists (GLP-1 RA) and dipeptidyl peptidase-4 inhibitors (DPP-4i), have been last introduced in the pharmacological treatment of type 2 diabetes." (PMID 22761607, 2012). "The glucagon-like peptide-1 receptor (GLP-1R) agonists and dipeptidyl peptidase-4 (DPP-4) inhibitors have become important options for the management of patients with type 2 diabetes mellitus." (PMID 22390369, 2012). "Glucagon-Like Peptide-1 receptor agonists (GLP-1RAs), approved as glucose-lowering drugs for the treatment of type 2 diabetes, have also been shown to reduce body weight." (PMID 22675341, 2012). "Regulation of GIPR and GLP-1R by N-glycosylation may have important implications for type 2 diabetes (T2DM)." (PMID 22412906, 2012). "Glucagon-like peptide-1 receptor agonists (GLP-1RAs), widely used for type 2 diabetes and obesity, have emerged as multi-target candidates for ocular therapeutics due to their pleiotropic anti-inflammatory, antioxidant, vasculoprotective, and neuroprotective properties." (PMID 41683853, 2026). "This phenomenon may be relevant to the optimal targeting of the glucagon-like peptide-1 receptor (GLP-1R), a type 2 diabetes and obesity target GPCR for which several ligands with varying internalisation tendency have been discovered." (PMID 41391570, 2026). "Glucagon-like peptide-1 receptor agonists (GLP-1 RAs), a class of antihyperglycemic drugs, are used to manage type 2 diabetes mellitus, but also have pleiotropic effects on protecting against age-related oxidative stress, cellular senescence, and chronic inflammation." (PMID 40844600, 2025). "By maintaining high-affinity binding and inducing prolonged activation of GLP-1R, dulaglutide effectively enhances insulin secretion, inhibits glucagon release, and delays gastric emptying—mechanisms critical for glycemic control in type 2 diabetes mellitus (T2DM)." (PMID 41226200, 2025). "Glucagon-like peptide-1 receptor agonists (GLP-1RAs), widely used for obesity and type 2 diabetes, have demonstrated pleiotropic benefits that include reductions in systemic inflammation, improvement of myocardial energetics, and attenuation of adverse structural remodeling." (PMID 41374408, 2025). "Glucagon-like peptide-1 receptor agonists (e.g., semaglutide and liraglutide) (GLP-1 RA) were first approved by the Food and Drug Administration (FDA) in 2005 for the treatment of Type 2 Diabetes but have only recently revolutionized the market as a weight loss drug for the non-diabetic patient." (PMID 41295856, 2025). "Glucagon-like peptide-1 receptor agonists (GLP-1 RAs) and sodium-glucose cotransporter-2 inhibitors (SGLT2is), initially developed for managing type 2 diabetes, have shown CV and renal protective effects, alongside emerging evidence of their role in modulating cancer-related metabolic pathways." (PMID 40364115, 2025).
type 2 diabetes (continued). "The glucagon-like peptide-1 receptor (GLP-1R), which belongs to the class B1 G protein-coupled receptor (GPCR) family, is an important target for treatment of metabolic disorders, including type 2 diabetes and obesity." (PMID 40807391, 2025). "Tirzepatide is a dual incretin receptor agonist that interacts with both the glucose-dependent insulinotropic polypeptide receptor (GIPR) and the glucagon-like peptide-1 receptor (GLP-1R), contributing to its therapeutic effects in type 2 diabetes (T2D) and obesity." (PMID 41226200, 2025). "Glucagon-like peptide-1 receptor agonists (GLP-1RAs), initially developed for the treatment of type 2 diabetes, have demonstrated pleiotropic effects that may be beneficial in the septic context." (PMID 41357527, 2025). "Glucagon-like peptide-1 receptor agonists (GLP-1 RAs), developed for type 2 diabetes and obesity, may also reduce alcohol consumption by modulating central reward pathways." (PMID 41324012, 2025). "For example, glucagon-like peptide-1 receptor agonists (GLP-1 RAs) have demonstrated significant cardiovascular risk reduction in patients with obesity and type 2 diabetes, independent of their effects on lipid levels." (PMID 40943795, 2025). "This information suggests that the presence of GLP-1R could indicate early-stage prostate cancer, and using a GLP-1RA could be a treatment for patients with type 2 diabetes mellitus and early-stage prostate cancer complications." (PMID 39429275, 2024). "Renal outcomes in patients with type 2 diabetes following treatment with sodium–glucose co-transporter-2 inhibitors (SGLT2is) or glucagon-like peptide-1 receptor agonists (GLP1RAs) have not been directly compared." (PMID 38956548, 2024). "The most promising drug with GLP-1R/GIPR dual agonist effects is Tripeptide (LY3298176), developed by Eli Lilly and Company, which the Food and Drug Administration (FDA) has approved for treating type II diabetes and obesity." (PMID 39030216, 2024). "Recently, our real-world data study has mirrored outcomes from RCTs with SGLT2is, glucagon-like peptide-1 receptor agonists (GLP-1RAs) or combination therapy, with all three conferring mortality and cardiovascular protection in individuals with type 2 diabetes over 5 years." (PMID 39120767, 2024). "A recent exploratory analysis of four different phase 3 trials from the clinical development programs of both subcutaneous and oral semaglutide, a glucagon like peptide-1 receptor agonist, showed that semaglutide reduced CRP compared to comparator drugs in individuals with type 2 diabetes." (PMID 38730445, 2024). "Glucagon-like peptide-1 receptor agonists are effective treatments for type 2 diabetes, effectively lowering glucose without weight gain and with low risk for hypoglycemia." (PMID 37423944, 2023). "Liraglutide, a GLP-1R agonist, is FDA-approved for treatment of type 2 diabetes, obesity and for secondary prevention of myocardial infarction, stroke and cardiovascular death in people with type 2 diabetes and established cardiovascular disease." (PMID 38096190, 2023). "This study aimed to clarify the renal influence of glucagon-like peptide 1 receptor agonists (GLP1Ras) with or without sodium-glucose co-transporter 2 inhibitors (SGLT2is) on Japanese patients with type 2 diabetes mellitus (T2DM)." (PMID 37779602, 2023). "This suggests that, in type 2 diabetes, β cells do not have increased dependency on glucagon signaling via the GLP1R to maintain insulin secretion." (PMID 37751301, 2023). "Already, the GLP-1 receptor (GLP-1R) agonist has been used against obesity and type 2 diabetes." (PMID 37371472, 2023). "In opposition, GLP1R expression in the adipose tissue is not significantly altered with insulin resistance, prediabetes, or type 2 diabetes onset, in the human visceral adipose tissue." (PMID 36768789, 2023). "In people without type 2 diabetes, exendin 9-39 — presumably through GLP1R blockade — decreases insulin secretion in response to glucagon." (PMID 37751301, 2023).
type 2 diabetes (continued). "We applied the methods to an illustrative example in type 2 diabetes assessing the impact of treatments within two classes of glucose-lowering medications; sodium-glucose co-transporter 2 inhibitors (SGLT-2is) and glucagon-like peptide-1 receptor agonists (GLP-1RAs)." (PMID 37087450, 2023). "However, glucagon-like peptide-1 receptor agonists (GLP-1RAs), already approved for treating type 2 diabetes, have lately emerged as possible treatments." (PMID 37511368, 2023). "In a phase 3 clinical trial, tirzepatide, a dual GIPR/GLP1R agonist, was shown to confer superior HbA1c control as compared to GLP1R agonism alone and has recently been approved by the U.S. Food and Drug Administration (FDA) for type 2 diabetes treatment." (PMID 37250804, 2023). "GLP-1R is not expressed at the mRNA level in type 2 diabetes mellitus patients’ PBMCs or THP-1 monocytes." (PMID 37266425, 2023). "Infusion of exendin 9-39 — a competitive antagonist of the GLP1R in people without type 2 diabetes — resulted in a small but significant increase in fasting glucose concentrations." (PMID 37751301, 2023). "GLP1R was upregulated in beta cells from individuals with type-2-diabetes (p<0.0001) whereas the remaining genes were not differentially expressed (p>0.05)." (PMID 35325259, 2022). "Dipeptidyl peptidase 4 inhibitors, glucagon-like peptide 1 receptor (GLP-1R) agonists, and sodium-glucose cotransporter-2 (SGLT2) inhibitors have been rigorously evaluated through cardiovascular outcomes trials in the management of type 2 diabetes." (PMID 36561085, 2022). "Since the PVN plays a role in energy balance and glucose homeostasis, in which its GLP-1R neurons are likely involved, we hypothesized that GLP-1R in the nucleus may be affected in type 2 diabetic patients." (PMID 36555587, 2022). "Clinical studies have reported that both sodium-glucose cotransporter-2 inhibitors (SGLT2i) and glucagon-like peptide-1 receptor agonists (GLP-1RA) reduce body weight and risks of major adverse cardiovascular events (MACE) and/or hospitalization for HF in patients with type 2 diabetes." (PMID 35765074, 2022). "New hypoglycemic drugs, including glucagon-like peptide 1 receptor agonists (GLP-1RA), dipeptidyl peptidase-4 inhibitors (DPP-4i) and sodium-glucose cotransporter 2 inhibitors (SGLT-2i), which brings more options for the treatment of type 2 diabetes (T2DM)." (PMID 35865956, 2022). "Numerous endogenous agonists activate the GLP-1R, including several forms of GLP-1, oxyntomodulin and glucagon, and multiple exogenous peptide agonists are approved, or in clinical development, for the treatment of type 2 diabetes and/or obesity." (PMID 35013280, 2022). "Interestingly, a decreased expression of GLP-1R in the paraventricular (PVN) and infundibular (IFN) (arcuate) hypothalamic nuclei was observed in patients with type 2 diabetes mellitus." (PMID 36499229, 2022). "In addition, immunofluorescence results have confirmed that the GLP-1R protein is present and more abundant in VAT than in SAT in individuals with type 2 diabetes." (PMID 35797355, 2022). "The extracellular domain of the glucagon-like peptide-1 receptor, GLP-1R, is responsible for the binding of GLP-1, and a handful of additional agonists (such as exenatide, lixisenatide, and liraglutide) used daily for treating type II diabetes mellitus." (PMID 36128537, 2022). "Glucagon-like peptide-1 receptor agonists are promising in obesity-related CKD since they have shown benefits in terms of losing weight in obese patients, as well as preventing the onset of macroalbuminuria and slowing the decline of eGFR in type 2 diabetes." (PMID 33928108, 2021). "Recent clinical trials of glucose-lowering therapies including glucagon-like peptide 1 receptor agonists (LEADER trial) and sodium–glucose cotransporter-2 inhibitors (EMPA-REG OUTCOME trial), report beneficial cardiovascular disease outcomes in type 2 diabetes patients." (PMID 34690762, 2021).
type 2 diabetes (continued). "To date, no treatment is available for WS, although there are some promising drugs against the progression of WS—two of which are the glucagon-like peptide-1 receptor (GLP-1R) agonist liraglutide (LIR), used for the treatment of type 2 diabetes, and mood stabilizer valproic acid (VPA)." (PMID 34828323, 2021). "Activation of the GLP-1R augments glucose-stimulated insulin secretion, and GLP-1 mimetics and dipeptidyl peptidase-4 inhibitors (which block degradation of GLP-1) are used in the treatment of type 2 diabetes." (PMID 33784857, 2021). "A previous study has shown that the combination of GLP-1R agonist and angiotensin receptor blocker (ARB) increases natriuresis compared to GLP-1R agonist alone in Otsuka Long–Evans Tokushima Fatty rats, a model of obese type 2 diabetes." (PMID 32384887, 2020). "The incretin effect resulting from targeting GLP-1R led to the successful commercialization of three short-acting agonists [exenatide, lixisenatide, and liraglutide] and three long-acting agonists [bydureon, dulaglutide, and semaglutide] as therapeutics for type 2 diabetes (T2D)." (PMID 32481528, 2020). "G protein-biased ligands for GLP-1R have been shown to enhance insulin secretion in mouse models of type 2 diabetes without producing nausea, a common adverse effect of GLP-1R agonists, thus allowing higher doses to be used." (PMID 31330984, 2019). "Although GLP-1R agonist increased insulin-stimulated glucose uptake in fat derived cells under normal condition, whereas the clinical indications of GLP-1 were obesity and obesity-related type 2 diabetes." (PMID 30459598, 2018). "The available non-insulin injectable medications for type 2 diabetes include pramlintide and several medications in the class of glucagon-like peptide-1 receptor agonists (GLP-1 RAs)." (PMID 30294713, 2018). "Glucagon-like peptide-1 receptor agonists (GLP-1RAs) are indicated with diet and exercise for the improvement of glycemic control in adults with type 2 diabetes mellitus (T2DM), many of whom are taking background oral glucose-lowering medications such as metformin and sulfonylureas." (PMID 29397532, 2018). "The first cardiovascular outcome trial on glucagon-like peptide-1 receptor agonists was the ELIXA trial, which was designed to assess the effects of lixisenatide on the cardiovascular outcome in patients with type-2 diabetes mellitus who had an acute coronary event within 180 days of screening." (PMID 28894748, 2017). "GLP-1R is initially found expressing in pancreatic islets cells and activated GLP-1R induces insulin synthesis and release; thus, GLP-1R agonists or dipeptidyl peptidase 4 (DPP-4) inhibitors have been used in the treatment of type 2 diabetes mellitus (T2DM)." (PMID 28846606, 2017). "The glucagon-like peptide-1 receptor (GLP-1R) is a class B GPCR that has proved to be an effective therapeutic target as several peptide-based agonists have been developed and registered for treating type 2 diabetes mellitus." (PMID 26975372, 2016). "The advent of exenatide, a glucagon-like peptide-1 receptor agonist provides a useful basis for managing type 2 diabetes and related cardiovascular complications without the side effects of regular diabetes therapies." (PMID 27669277, 2016). "Synthetic GLP1 receptor (GLP1R) agonists lower blood pressure in patients with type 2 diabetes through mechanisms not fully comprehended." (PMID 24327600, 2014). "The aim of this study was therefore to analyse the levels of DNA methylation of the GLP1R promoter in human pancreatic islets from 55 non-diabetic organ donors and 10 donors with type 2 diabetes." (PMID 23879380, 2013). "In agreement with previous studies, we found that GLP1R expression was reduced in pancreatic islets from donors diagnosed with type 2 diabetes compared with non-diabetic donors (type 2 diabetic 213±76.6 vs. non-diabetic 390.4±170.2, p=0.0006)." (PMID 23879380, 2013).